BRCA1 (BRCA1 DNA repair associated)
Diseases named in the same sentence as BRCA1 in open-access papers (continued):
Sharing a sentence is not in itself a finding about the gene and the disease.
ovarian carcinoma (continued). "Of these, BRCA1 and BRCA2 appear to account forapproximately two-thirds of germline mutations in ovarian cancer, with smallercontributions from the remaining genes." (PMID 26669451, 2015). "The identification of BRCA1/2 carriers is a critical component of breast and ovarian cancer prevention as there are multiple screening, surgical, and chemoprevention strategies that can be employed." (PMID 26543556, 2015). "We therefore sought to identify BRCA1/2-directed miRNA signatures that have prognostic value in ovarian cancer patients with wild-type BRCA1/2 and study how the deregulation of miRNAs impacts the prognosis of patients treated with platinum-based chemotherapy." (PMID 25537514, 2015). "BRCA1 and BRCA2 germline mutations are associated with high penetrance for both breast and ovarian cancer." (PMID 25366421, 2015). "Mutations of the tumor suppressor genes BRCA1 and BRCA2 are known to be associated with different patterns of hereditary breast and ovarian cancer." (PMID 25885768, 2015). "BRCA1 carriers should be advised to avoid oral contraceptive use if the purpose is to prevent ovarian cancer before the age of 25 (IIB)." (PMID 26669313, 2015). "This is typically older than the average age at which BRCA1/2-related breast and ovarian cancers occur." (PMID 26236408, 2015). "Germline losses in BRCA1/BRCA2 are highly penetrant, conferring 60–80 % risk of breast and 30–40 % risk of ovarian cancers." (PMID 26427375, 2015). "The tumor suppressors BRCA1 and BRCA2 play a central role in the maintenance of chromosomal stability and germline mutations in BRCA1 and BRCA2 genes have been detected in approximately 90% of hereditary breast/ovarian cancers." (PMID 26779440, 2015). "The benefits of BRCA1 and BRCA2 testing for women with breast and/or ovarian cancers, women with a family history and/or elevated risk, or even all women, are evident." (PMID 26543556, 2015). "Identifying carriers of BRCA1 and BRCA2 mutations allows for the targeted prevention of ovarian cancer in family members of ovarian cancer patients." (PMID 25884701, 2015). "The aim of this study was to detect BRCA1/BRCA2 aberrant transcripts resulting from alternative splicing, in women with a known family history and/or early onset of breast and/or ovarian cancer, tested wild-type for BRCA1 and BRCA2." (PMID 25683334, 2015). "Several FA genes are also breast and ovarian cancer susceptibility genes (FANCD1/BRCA2, FANCJ/BRIP1, FANCN/PALB2, FANCO/RAD51C, and FANCS/BRCA1)." (PMID 26430909, 2015). "Mutations in the BRCA1 and BRCA2 genes lead to an increased risk of developing breast or ovarian cancer as part of hereditary breast-ovarian cancer syndrome." (PMID 25859162, 2015). "To analyze the prevalence of HBOC with BRCA1 and BRCA2 germline mutations, we recruited 135 breast and/or ovarian cancer survivors and extracted DNA from their peripheral blood lymphocytes." (PMID 25802882, 2015). "For example, women carrying highly penetrant mutations in the BRCA1 and BRCA2 genes have an elevated risk of developing breast (BRCA1/2 carriers, 36–90%) and ovarian cancer (BRCA1 carriers, 24–59%; BRCA2 carriers, 8–35%)." (PMID 26325576, 2015). "The likelihood of harbouring a germline BRCA1/BRCA2 mutation depends on the histological subtype and/or tumour grade of epithelial ovarian cancers." (PMID 25884701, 2015). "Magnetic resonance imaging (MRI) screening is effective in detecting early cancers in BRCA1/2 carriers; mastectomy and oophorectomy can reduce ovarian cancers; and estrogen inhibition can reduce both type of malignancy." (PMID 26543556, 2015). "BRCA1 and BRCA2 mutations in ovarian cancers, are associated with defects in homologous recombination and genomic instability." (PMID 25537514, 2015). "The most common examples are represented by the inactivating mutations in BRCA1/2 and RAD51 in breast and ovary cancer." (PMID 26295265, 2015).
ovarian carcinoma (continued). "Inactivating germline mutations of BRCA1 and BRCA2 genes account for approximately 15% to 20% of hereditary breast and/or ovarian cancer (HBOC) cases." (PMID 24516540, 2014). "Women harboring a germ-line mutation in the BRCA1 or BRCA2 genes have a high lifetime risk to develop breast and/or ovarian cancer." (PMID 24698998, 2014). "Initial attempts at clinical translation of PARP inhibition relied on a strategy of synthetic lethality targeting genetically vulnerable tumors such as BRCA1- and BRCA2-deficient breast and ovarian cancers." (PMID 25124282, 2014). "Based on the diagnostic criteria used in the United States to select patients to be tested, clearly pathogenic mutations in either BRCA1 or BRCA2 are found in 10% to 15% of hereditary breast and ovarian cancer families." (PMID 25136623, 2014). "Previously reported estrogen-dependent cancer genes including classical breast and ovarian cancer genes (e.g. BRCA1, BRCA2 and CHK2) as well as novel genes were scored in the screen." (PMID 25238049, 2014). "Germline mutations that inactivate BRCA1 and BRCA2 are responsible for breast and ovarian cancer susceptibility." (PMID 25136594, 2014). "In summary, we have identified at least two SNPs, rs1466785 and rs2304277, in the DNA glycolylases NEIL2 and OGG1, potentially associated with increased breast and ovarian cancer risks in BRCA2 and BRCA1 mutation carriers, respectively." (PMID 24698998, 2014). "Characteristics of studies of patients of ovarian cancer with low BRCA1 mRNA expression or BRCA1 promoter methylation." (PMID 24788697, 2014). "Germ-line mutations in BRCA1 and BRCA2 tumor suppressor genes cause a hereditary predisposition to breast and ovarian cancer." (PMID 24906410, 2014). "One study demonstrated alterations of BRCA1 and/or 2 in up to 82% of examined ovarian cancers (n = 92)." (PMID 24579064, 2014). "We therefore, initially examined the expression of BRCA1 and caveolin-1 in a BRCA1-mutant human ovarian cancer cell line, UWB1.289." (PMID 25594072, 2014). "Women with BRCA1 and BRCA2 mutation carriers are at substantially elevated risk of developing ovarian cancer." (PMID 25494812, 2014). "In particular, inherited mutations in the HR mediators BRCA1 and BRCA2 are associated with increased risk of breast and ovarian cancer, and BRCA-mutated ovarian cancers show distinct therapeutic responses." (PMID 24829461, 2014). "BRCA1 and BRCA2 genes are critical in homologous recombination DNA repair and have been implicated in familial breast and ovarian cancer tumorigenesis." (PMID 25526776, 2014). "Various experimental procedures were performed with the same cut-off value (<10% positive cells) except for one study, and the summary proportion of low expression of BRCA1 (with cut-off value as <10% positive cells) in sporadic ovarian cancer was 55.2%." (PMID 24788697, 2014). "BRCA1 and BRCA2 are major susceptibility genes that confer high lifetime risks for both breast and ovarian cancer." (PMID 25274085, 2014). "Since 1996 genetic testing to identify mutations in BRCA1 and BRCA2 has been offered to women with a family history of breast and ovarian cancer." (PMID 24845084, 2014). "Our lab has identified and cloned two major isoforms of BRCA1, namely BRCA1a/p110 and BRCA1b/p100, which are the most evolutionary conserved of all the isoforms and expressed at reduced levels in ovarian cancers compared to normal cells." (PMID 25594072, 2014). "Such variants in the BRCA1 3’UTR have recently been identified and were first implicated in breast and ovarian cancer susceptibility in high-risk families." (PMID 24915755, 2014). "Deleterious mutations in the BRCA1 or BRCA2 genes increase a woman's lifetime risk of breast and ovarian cancer." (PMID 24586286, 2014). "Mutations of BRCA1 and BRCA2 tumor suppressor genes are responsible for most hereditary ovarian cancers." (PMID 24821107, 2014).
ovarian carcinoma (continued). "Only the Israeli study, therefore, like here reported ovarian cancer data, reported an actually inverted picture of more low FMR1 alleles in BRCA1/2-negative than BRCA1/2-positive women." (PMID 25036526, 2014). "There is no compelling evidence showing that the haploinsufficiency or low expression of BRCA1/2 gene predicts improved outcome for ovarian cancer." (PMID 25437005, 2014). "We next decided to implement our parallel pyrosequencing protocol and sequence analysis approach to screen for mutations in the BRCA1 and BRCA2 genes in a series of 101 patients with breast and ovarian cancer." (PMID 25136594, 2014). "BRCA1 knockdown effectively inhibited the expression of GR in SKOV3 cells and primary non-BRCA1-mutated ovarian cancer cells." (PMID 24629067, 2014). "Genetic depletion of BRCA1 resulted in significant loss of viability in CCNE1-amplified cells, including the ovarian cancer cell line OVCAR3, whereas a lesser effect was observed in CCNE1-wildtype cells, such as the SKOV3 cell line." (PMID 24624361, 2014). "Two variants 5711 + 421 T/T and 5711 + 1286 T/T (located in the BRCA1 3’UTR) are associated with cancer risk in Thai women from breast and ovarian cancer families (OR = 3.0)." (PMID 24915755, 2014). "BRCA1 epigenetic inactivation has been reported in ovarian cancer, and has been recently proven to be a predictor of enhanced sensitivity to platinum-based chemotherapy." (PMID 25437005, 2014). "HSP90 inhibition sensitized BRCA1-proficient breast and ovarian cancer cells in vitro to carboplatin treatment at concentrations similar to BRCA1-mutant cells." (PMID 24624361, 2014). "Ovarian cancers associated with BRCA mutations, particularly BRCA1, present at a younger age compared to sporadic cases." (PMID 27382614, 2014). "According to the updated data in TCGA, BRCA1 and BRCA2 were non-synonymously mutated in 42 and 33 ovarian cancer cases, respectively, accounting for 12.9% and 10.1% of 325 patients." (PMID 25437005, 2014). "FasL/Fas interactions have previously been shown to play an important role in mediating BRCA1-dependent apoptosis in breast and ovarian cancer cells." (PMID 25594018, 2014). "Screening for mutations in the tumor suppressor genes BRCA1 and BRCA2 is of great significance for breast and ovarian cancer prevention and early detection." (PMID 24884479, 2014). "Methylation of the BRCA1 promoter has been demonstrated in up to 14% of sporadic breast and up to 30% of sporadic ovarian cancers." (PMID 24579064, 2014). "One of the most studied genes in ovarian cancer is breast cancer early onset gene 1 (BRCA1) gene, due to its role in inherited and sporadic forms of the disease." (PMID 24821107, 2014). "Preventive bilateral salpingo-oophorectomy is effective method to reduce ovarian cancer incidence in BRCA1 carriers, improve survival and should be advocated after 35 years of age when childbirth is completed." (PMID 24770866, 2014). "Majority of mutations found to date in the BRCA1/BRCA2 genes in breast and/or ovarian cancer families are point mutations or small insertions and deletions scattered over the coding sequence and splice junctions." (PMID 24906410, 2014). "Recently, next generation sequencing methods for the mutation analysis of the BRCA1 and BRCA2 genes in patients with breast and ovarian cancer have been described using both high capacity and bench top platforms." (PMID 25136594, 2014). "The strongest evidence of association found in BRCA1 carriers was between rs2304277 in the OGG1 gene and ovarian cancer risk." (PMID 24698998, 2014). "For example, previous studies showed that cases with BRCA1/2 mutations have better overall survival than those with wild type BRCA1/2 in patients with ovarian carcinoma." (PMID 25390899, 2014).
ovarian carcinoma (continued). "A study using methylation-specific PCR to screen ovarian tumor samples for six tumor suppressor genes (BRCA1, RASSF1A, APC, p14ARF, p16INK4a, and DAP-kinase) indicated that this “hyper-methylation panel” provides diagnostic information in ovarian cancer." (PMID 24782983, 2014). "Mutations in BRCA1 or BRCA2 are found in the majority of hereditary breast and ovarian cancers and greatly increase lifetime risk for both cancers." (PMID 24624361, 2014). "There are well described cases of gene regulation in ovarian cancer relying on hyper- or hypomethylation, including down-regulation of both BRCA1 and the PTEN tumor suppressors by promoter hypermethylation." (PMID 24971229, 2014). "Accumulating evidence indicates that hereditary factors (e.g., BRCA1) and epigenetic events are involved in the initiation and progression of ovarian cancer." (PMID 24448423, 2014). "In one study, the frequencies of methylation in the BRCA1 promoter region were examined in 96 sporadic invasive breast carcinomas and 43 sporadic ovarian carcinomas." (PMID 25051360, 2014). "In order to evaluate the effect of 17-AAG in HR deficient ovarian cancer cells, we used the OVCAR8 cell line which harbors almost undetectable levels of BRCA1 protein and very low levels of BRCA1 transcript compared to 36M2 ovarian cancer line." (PMID 24798692, 2014). "TNRC9 and BRCA1 protein expression were inversely correlated in large data sets of breast and ovarian cancer samples." (PMID 25051360, 2014). "The HDAC inhibitor M344, which is specific for HDAC6 and to a lesser extent HDAC1, has been shown to promote growth inhibition, cell cycle arrest, and apoptosis, as well as inhibit BRCA1 expression in ovarian cancer cell lines." (PMID 24971229, 2014). "A germline, variant in the BRCA1 3’UTR (rs8176318) was previously shown to predict breast and ovarian cancer risk in women from high-risk families, as well as increased risk of triple negative breast cancer." (PMID 24915755, 2014). "Mutations in the BRCA1 and BRCA2 genes confer high susceptibility to both breast and ovarian cancer." (PMID 24742220, 2014). "Using our validated workflow, we have identified 18 deleterious mutations in 101 patients (17,8%) which is in accordance with the prevalence of BRCA1 and BRCA2 mutations reported in the Spanish hereditary breast and ovarian cancer population." (PMID 25136594, 2014). "In vitro and in vivo experiments suggest that this BRCA1-JunB interaction is particularly important for the suppression of ovarian cancer." (PMID 24137399, 2013). "Consistent with this idea, we showed that ovarian cancer tissue with a hypermethylated BRCA1 promoter (P < 0.05) displayed reduced expression of BRCA1 (P < 0.05) compared with adjacent normal tissue." (PMID 24321281, 2013). "The prevalence of BRCA1 and BRCA2 mutations in ovarian cancer patients varies amongst populations; a quite thorough population study in North America demonstrates a 13–15% frequency of germline BRCA1/2 mutations in sporadic ovarian cases." (PMID 23536787, 2013). "Rare germline mutations of BRCA1 and BRCA2 predispose carriers to early-onset familial breast or ovarian cancers." (PMID 23704879, 2013). "In ovarian cancer, BRCA1 promoter is hypermethylated in 31% of sporadic ovarian carcinomas with loss of heterozygosity at BRCA1 locus." (PMID 23873296, 2013). "Both rs17631303 and rs183211 were associated with ovarian cancer risk for BRCA2 carriers (P = 1.98×10−4 and 9.26×10−4), with similar magnitude and direction of association as for BRCA1 carriers." (PMID 23544013, 2013). "The potential contradictory effects of BRCA1 on the two most common agents used to treat advanced ovarian cancer make it difficult to appreciate how alterations in BRCA1 mediate tumor response in patients treated with a combination of C + P." (PMID 23964347, 2013). "Both preclinical and clinical data suggest that alterations in BRCA1 or BRCA2 have prognostic value in ovarian cancer." (PMID 23964347, 2013).
ovarian carcinoma (continued). "For women who carry the deleterious mutation in either of the BRCA genes, BRCA1 or BRCA2, the risk of developing breast or ovarian cancer is significantly increased." (PMID 23517070, 2013). "In this study, a large deletion overlapping exons 1A-13 of BRCA1 was observed in one individual with BC diagnosed at age 46 years and with ovarian cancers diagnosed in her mother and half-sister (family 252)." (PMID 23967248, 2013). "In addition, upcoming trials of PARP inhibitors in ovarian cancer that specifically enrich for BRCA1 and BRCA2 carriers may be at particular risk for confounding biases in treatment response if differences in between these two biologically distinct groups are not considered." (PMID 24349831, 2013). "Mutations in the breast and ovarian cancer-susceptibility genes, BRCA1 and BRCA2, confer an increased lifetime risk of ovarian cancer." (PMID 23591842, 2013). "In summary, we have identified a number of Notch proteins as key transcriptional targets of the breast/ovarian cancer tumour suppressor gene BRCA1." (PMID 23863842, 2013). "Additional functional characterisation of the loci will further improve our understanding of the biology of breast and ovarian cancer development in BRCA1 carriers." (PMID 23544013, 2013). "Consistent with this idea, we showed that ovarian cancer tissue with a hypermethylated BRCA1 promoter displayed decreased expression of BRCA1 in comparison with adjacent normal tissue (Figure 3Aii and Bi, P < 0.05)." (PMID 24321324, 2013). "Further studies are warranted to determine the prevalence of mutations in the rest of the BRCA1 gene, in the BRCA2 gene, and other novel predisposing genes for breast and ovarian cancer." (PMID 23536787, 2013). "Our results show the same associations between tumor Nmut and treatment outcome in both BRCA1- and BRCA2-associated ovarian cancers." (PMID 24265793, 2013). "A Canadian study of 1342 ovarian cancer cases revealed a combined mutation frequency of 13.3% of both BRCA1 and BRCA2, 8% of which was BRCA1." (PMID 23536787, 2013). "Other lines of evidence show differences between BRCA1 and BRCA2 mutation-associated ovarian cancers." (PMID 24265793, 2013). "The BRCA1 deletion encompassing exons 1A-13 has been reported in a Finnish breast/ovarian cancer family." (PMID 23967248, 2013). "BRCA1 and BRCA2 are tumor suppressor genes in which loss or inactivation increases the risk of hereditary breast and ovarian cancer." (PMID 23393598, 2013). "BRCA1 or BRCA2 mutations are a high-risk factor for HGSC, and women harboring such mutations have a 30% to 70% probability of developing ovarian cancer by the age of 70." (PMID 24063014, 2013). "Kang et al38 studied Chinese Malaysian families and found BRCA1 exon 1_14 deletion in 1 case with hereditary breast/ovarian cancer, with a 78 500 bp deletion." (PMID 23318652, 2013). "The BRIP1 protein, also known as FANCJ or BACH1, acts as a BRCA1- associated helicase, and mutations of BRIP1 also predispose to ovarian cancer with apparently higher penetrance." (PMID 24025454, 2013). "BRCA1 and BRCA2 mutation carriers in these families are at the same risk level for breast and ovarian cancer as women from high-incidence families." (PMID 23536787, 2013). "Nowadays, genetic testing is offered primarily to patients with early onset breast/ovarian cancer (<45 years) or when a strong family history is present, and it primarily involves analysis of BRCA1 and BRCA2 genes." (PMID 23536787, 2013). "Germline mutations in the BRCA1 and BRCA2 genes contribute to approximately 18% of hereditary ovarian cancers conferring an estimated lifetime risk from 15% to 50%." (PMID 23536787, 2013). "BRCA1 and BRCA2 are considered tumor suppressor genes, and loss-of-function mutations confer a significantly increased risk of developing breast and ovarian cancer." (PMID 23964347, 2013).